TMSB4X (thymosin beta 4 X-linked)
Diseases named in the same sentence as TMSB4X in open-access papers (continued):
Sharing a sentence is not in itself a finding about the gene and the disease.
glomerulonephritis (2 papers, 2016 to 2022). A renal disorder characterized by damage in the glomeruli. "Furthermore, N-acetyl-seryl-aspartyl-lysyl-proline, the N-terminal tetrapeptide generated by Tmsb4x cleavage, has beneficial effects on fibrosis and inflammation in unilateral ureteral obstruction, remnant kidneys, diabetic nephropathy, and glomerulonephritis." (PMID 27575556, 2016). "We postulate that endogenous Tmsb4x has a protective role in the setting of NTS, a prediction supported by a study showing that exogenous administration of Ac-SDKP ameliorated rat glomerulonephritis." (PMID 27575556, 2016).
head and neck squamous cell carcinoma (2 papers, 2017 to 2022). A squamous cell carcinoma that arises from any of the following anatomic sites: lip and oral cavity, nasal cavity, paranasal sinuses, pharynx, larynx, and salivary glands. "The overexpression of TMSB4X was found significantly associated with poor prognosis of overall survival and recurrence-free survival in head and neck squamous cell carcinoma (HNSCC) patients." (PMID 35631574, 2022).
liver diseases (2 papers, 2022 to 2024). "The role of TMSB4X (Thymosin beta 4) was already known in inflammation and liver diseases." (PMID 35681439, 2022).
nephritis (2 papers, 2016 to 2023). Inflammation of renal tissue. "Administration of NTS to Tmsb4x−/y mice also significantly increased plasma creatinine (P < 0.01), impaired creatinine clearance (P < 0.01), and raised the blood urea nitrogen level (P < 0.05) compared with Tmsb4x+/y mice with NTS nephritis." (PMID 27575556, 2016). "However, NTS administration to Tmsb4x−/y mice significantly reduced the number of WT1+ glomerular tuft cells compared with Tmsb4x+/y mice with NTS nephritis (P < 0.001)." (PMID 27575556, 2016).
osteosarcoma (2 papers, 2014 to 2024). A usually aggressive malignant bone-forming mesenchymal neoplasm, predominantly affecting adolescents and young adults. "Specifically, the EMT score of S100A1+ cells were significantly higher than that of TMSB4X+ and SLPI+ cells, suggesting that osteosarcoma cells in the TMSB4X+ cells exhibit a greater migration ability, possibly associated with an increased propensity for metastasis." (PMID 39742274, 2024).
papillary thyroid cancer (2 papers, 2024). "TMSB4X was found to be overexpressed in malignant and metastatic cells by analyzing the single‐cell transcriptome of papillary thyroid cancer, which indicates that it may participate in cancer progression." (PMID 38886907, 2024).
squamous cell carcinoma (2 papers, 2019 to 2023). A carcinoma arising from squamous epithelial cells. "TMSB4X is involved in intracellular signaling and has been found to be overexpressed in colorectal, lung, gastric, pancreatic, head and neck squamous, and squamous cell carcinomas." (PMID 37842637, 2023). "TMSB4X proteins regulate intracellular signal transduction and has been proved to overexpress in various cancers, including colorectal, lung, gastric, pancreatic, and squamous cell cancers." (PMID 31781249, 2019).
atherosclerosis (1 paper, 2023). A disease characterized by the build-up of fatty material and calcium deposition in the arterial wall resulting in partial or complete occlusion of the arterial lumen. "•Tmsb4x null mice are predisposed to atherosclerosis with dysregulated LRP1 signalling." (PMID 37724952, 2023). "By single cell transcriptomic analysis, Tmsb4x, encoding Tβ4, strongly correlated with contractile gene expression and was significantly down-regulated in cells that adopted a modulated phenotype in atherosclerosis." (PMID 37724952, 2023). "•Tmsb4x correlates with contractile phenotype and is downregulated in atherosclerosis." (PMID 37724952, 2023).
B cell lymphoma (1 paper, 2025). "TMSB4X encodes an actin-stabilizing protein which is downregulated in CSF-resident dural B cells, associated with an early immature B cell phenotype, and is a target of somatic mutations in B cell lymphoma." (PMID 39708811, 2025).
Cirrhosis (1 paper, 2022). A chronic disorder of the liver in which liver tissue becomes scarred and is partially replaced by regenerative nodules and fibrotic tissue resulting in loss of liver function. "Proteomic analysis revealed that faulty functionality of neutrophils may be due to the autophagy proteins i.e., DNAJC13, AHSG, TMSB4X, PROS1 and SERPINA3, which can be used as therapeutic targets in decompensated cirrhosis patients with sepsis." (PMID 35681439, 2022). "We conclude that the faulty functionality of neutrophils may be due to the autophagy proteins, i.e., DNAJC13, AHSG, TMSB4X, PROS1, and SERPINA3, which can be used as therapeutic targets in decompensated cirrhosis patients with sepsis." (PMID 35681439, 2022).
Crohn disease (1 paper, 2024). A gastrointestinal disorder characterized by chronic inflammation involving all layers of the intestinal wall, noncaseating granulomas affecting the intestinal wall and regional lymph nodes, and transmural fibrosis. "We painted the landscapes of monocyte-macrophages and identified 5 distinct subsets including monocytes, C1QB+ macrophages, HSPA1B+ macrophages, IL-1B+ macrophages, and TMSB4X + macrophages in the intestinal mucosa from Crohn’s disease patients." (PMID 39095853, 2024).
diabetic retinopathy (1 paper, 2012). "Using Wiki-Pi, we infer that its association to diabetic retinopathy may be mediated through its interactions with the genes HSPB1, KRAS, TMSB4X and DGKD, and that it may be involved in cellular response to external stimuli, cytoskeletal organization and regulation of molecular activity." (PMID 23209562, 2012).
diffuse large B-cell lymphoma (1 paper, 2021). "For example, TMSB4X, for which intronic mutations account for 67% of mutant samples, has recently been reported to be recurrently truncated in diffuse large B-cell lymphoma." (PMID 33420369, 2021).
emphysema (1 paper, 2023). "In the emphysema XWAS, the top suggestive association in all subjects was a variant in FRMPD4, located 332 kb upstream of the TMSB4X variant in the Xp22.2 locus; both FRMPD4 and TMSB4X escape XCI." (PMID 36726148, 2023).
epidermolysis bullosa (1 paper, 2020). Epidermolysis bullosa (EB) is a group of genetic skin diseases that cause the skin to blister very easily. "The function of TMSB4X in the skin is particularly relevant to human health, and TMSB4X peptides are being tested in clinical trials for the treatment of dermal ulcers and epidermolysis bullosa, a group of skin-blistering diseases." (PMID 33310787, 2020).
focal segmental glomerulosclerosis (1 paper, 2016). A renal disorder characterized by sclerotic lesions in the glomeruli. "In contrast, a previous study in rat remnant kidneys in which nephron loss results in focal segmental glomerulosclerosis showed that Tmsb4x protein levels were significantly increased in sclerotic versus normal glomeruli." (PMID 27575556, 2016).
insulinoma (1 paper, 2025). "Of potential relevance to the ongoing use of the tyrosine kinase inhibitor toceranib in canine insulinoma, TMSB4X is also reportedly overexpressed in toceranib-resistant liver cancer cell lines." (PMID 40438247, 2025).
Klinefelter syndrome (1 paper, 2019). A sex chromosome disorder caused by the presence of an extra X chromosome in the male karyotype. "Specifically, TMSB4X (a ‘probable’ escapee) was associated with ChrX dosage effect in Klinefelter syndrome, presumably due to its escapee characteristics." (PMID 30871455, 2019).
psoriasis (1 paper, 2022). An autoimmune condition characterized by red, well-delineated plaques with silvery scales that are usually on the extensor surfaces and scalp. "The authors also found that many psoriasis-specific DEPts were fragments of four proteins, namely fibrinogen α/FGA, filaggrin/FLG, thymosin beta-4/TMSB4X, and FLJ55606 (highly similar to alpha-2-HS-glycoprotein)." (PMID 35327421, 2022).
Sepsis (1 paper, 2022). Sepsis is defined as life-threatening organ dysfunction caused by a dysregulated host response to infection. "In sepsis, a significant decrease in TMSB4X levels activates the inflammatory cascade and is correlated with a decrease in mortality." (PMID 35681439, 2022). "Expression of TMSB4X was found to be significantly increased in sepsis (p = 0.038) compared to HC and DNAJC13 and AHSG were found to decrease in sepsis compared to w/o sepsis." (PMID 35681439, 2022).
tongue squamous cell carcinoma (1 paper, 2017). A squamous cell carcinoma that arises from the tongue. "Gene expression analysis from Microarray database in cell lines from human primary and metastatic tongue squamous cell carcinoma showed that TMSB4X gene is expressed at about 4-fold higher in metastatic cells than in primary cells." (PMID 28831179, 2017).
ulcers (1 paper, 2020). "Moreover, TMSB4X-derived peptides are being tested in clinical trials and have shown promising results for the treatment of ulcers and other slow-healing wounds." (PMID 33310787, 2020).
Ureteral obstruction (1 paper, 2016). Obstruction of the flow of urine through the ureter. "Tmsb4x reduced renal tubulointerstitial fibrosis after unilateral ureteral obstruction in mice, potentially through decreasing plasminogen activator inhibitor-1 expression and dampening transforming growth factor-β1 signaling." (PMID 27575556, 2016).
virus infection (1 paper, 2025). "TMSB4X was overexpressed in the cortex and hippocampus of 5xFAD mice after virus infection for 1.5 months." (PMID 40816274, 2025).
tumor (45 papers, 2008 to 2025). "According to our previous proteomic study from 2010 to 2017, thymosin beta-4 X-linked (TMSB4X) is related to tumor growth and the metastasis of HNSCC." (PMID 34442426, 2021). "Thymosin beta 4 X-linked (TMSB4X) levels changed dramatically, and this protein was identified as one of the most important candidate molecules contributing to the tumour-promoting effects of ADSCs." (PMID 31781249, 2019). "In the correlation analysis of clinicopathological features, the patients with high IHC expression of TMSB4X were found significantly associated with tumor recurrence (P = 0.017), and also presented poor overall survival rate (OS, P = 0.006) as well as recurrence-free survival rate (RFS, P = 0.013)." (PMID 28831179, 2017). "Spatial transcriptomics of CRC tumor cryosections revealed high expression of thymosin beta-4 (TMSB4X) in tumor cells - a protein involved in actin binding, cell migration, and inflammation." (PMID 41450739, 2025). "The higher expression of TMSB4X is consistent with the recent finding that TMSB4X is one of the markers of epithelial cells in CRC tumor tissue." (PMID 38729966, 2024). "Three of the top upregulated and most highly expressed DEGs in the majority of Ascl1-OE tumor cells are Tmsb4x, Sparcl1, and Mt3." (PMID 39609428, 2024). "The upregulation of TMSB4X is correlated with tumor progression and induces the activation of myocardin-related transcription factors (MRTF) that regulate EMT transition and downregulate E-cadherin." (PMID 36980828, 2023). "The most frequently mutated genes in the tumor tissue cohort were DTX1 (37%), CD79B (35%), BTG1 (30%), BTG2 (30%), and TMSB4X (30%)." (PMID 36280874, 2022). "CB2 stimulation reduces the expression of CD9, SEC61G, TBX21, and TMSB4X genes involved in tumor growth and progression, and also negatively affects downstream intracellular pathways." (PMID 35955786, 2022). "It was also reported by the subsequent investigations that TMSB4X contributes to tumor aggressiveness through epithelial-mesenchymal-transition (EMT) in pancreatic, gastric, colorectal, lung, ovarian, and melanoma cancers." (PMID 34442426, 2021). "TMSB4X and CD109 were also associated to tumor conditions, being as well able to discriminate PA from all other tumors." (PMID 33469081, 2021). "At the protein level, immunohistochemistry (IHC) staining also revealed an evidently higher expression of TMSB4X on tumor cells compared with their adjacent normal thyrocytes in two additional cases (a classical PTC and an FV-PTC)." (PMID 34663816, 2021). "Next we found out that metastatic cell lines expressed TMSB4X at higher level when compared to cell lines isolated from primary tumor sites." (PMID 31921836, 2019). "Previously, TMSB4X was reported to induce the EMT by activating integrin-linked kinase (ILK) and the TGF beta signalling pathway to promote tumour progression." (PMID 31781249, 2019). "We inhibited TMSB4X expression with a specific shRNA to determine TMSB4X's role in the tumour-promoting effects of ADSCs." (PMID 31781249, 2019). "Higher TMSB4X expression in the tumor was found by N/T-paired HNSCC samples at both RNA and protein level." (PMID 28831179, 2017). "In tumor cells, TMSB4X can promote cell migration and vascular endothelial growth factor-induced angiogenesis, thereby accelerating tumor growth and metastasis." (PMID 25889491, 2015). "For the tumor region, a typical feature of TMSB4X-high expression was identified, which could be a potential marker of CRC." (PMID 38729966, 2024). "Similarly, immune/inflammation-related TFs, such as NFKB2, STAT1, and RELA, and FOXO3, showed high activity in CXCL10+MEL and TMSB4X+MEL subclusters, which underlies the immunomodulatory phenotype of tumor cells." (PMID 38065972, 2023).
tumor (continued). "qPCR quantification of the relative expression of the five candidate genes LOXL1, SCRN1, VAMP5, SERPINB1, and TMSB4X in cryopreserved tumor tissues from validation set 1 was correlated to the CSIs measured in the corresponding fresh tissue samples of the same tumor lesions." (PMID 26799424, 2016). "Additionally, in other architecture-dependent tissues whose spatial locations are deeply intertwined with their functions, such as brain and heart, TMSB4X has been reported to be involved in tumor progression via neovascularization, cell adhesion and the epithelial-mesenchymal transition." (PMID 38729966, 2024). "Thus, it might be suggested that TMSB4X is a candidate for tumor type-agnostic therapy, as a common biomarker of several types of cancer." (PMID 34442426, 2021). "miR-1 acts as a tumor suppressor, promoting the inhibition of tumor growth and acting with multiple target genes, such as CDK4, TMSB4X, WASF2, TWF1, CNN3, and CORO1C which are genes involved in cell cycle and metastasis." (PMID 38813102, 2024). "In this regard, Thymosin-ß4 (Tß4; TMSB4X) and THBS1 are considered as tumor promoters with a poor prognosis in different types of cancers." (PMID 32793473, 2020). "TMSB4X is a candidate regulator of cancer progression and metastasis, such as ADSC-mediated tumour progression that is involved in regulating the interaction between the TME and primary tumour." (PMID 31781249, 2019). "The results showed that the expression of SH2D2A and TERF2IP genes was significantly upregulated in the tumor tissues, whereas the expression of TMSB4X, although also elevated, was not statistically different." (PMID 37842637, 2023). "The expression levels of SH2D2A, TERF2IP, and TMSB4X were significantly different between normal and tumor samples of TCGA, while other model genes were not significantly different." (PMID 37842637, 2023). "Furthermore, we knocked down TMSB4X in HNSCC cell line and found that tumor growth and metastasis is attenuated." (PMID 28831179, 2017). "The expression level of TMSB4X in HNSCC was objected to being validated by an RT-PCR and real-time PCR in 35 pairs of the fresh-frozen HNSCC samples (T) and adjacent non-tumor tissues (N), and from 23 NT-paired dataset from the public HNSCC microarray cohort (GSE31056)." (PMID 28831179, 2017). "Moreover, we noted a noteworthy increase in the expression of TMSB4X within tumor tissues, although statistical significance was not firmly established." (PMID 37842637, 2023). "TMSB10 and TMSB4X expression were higher in patients with the C2 and C6 subtypes, which indicate a poorer prognosis, suggesting that TMSB10 and TMSB4X might be involved in tumor immune deregulation." (PMID 36163046, 2022). "However, the available evidence did not reveal a role for TMSB4X in regulating the interaction between the TME and primary tumour." (PMID 31781249, 2019). "Non-histone chromosomal protein HMG-17 (HMGN2), thymosin beta-4 (TMSB4X), 10 kDa heat shock protein (HSPE1), and the ratio between citrullinated/uncitrullinated GFAP fragment 388–432 showed significantly higher levels in ST-EPs, therefore marking the ST tumor location." (PMID 32183175, 2020).